TCF3 (transcription factor 3)
Diseases named in the same sentence as TCF3 in open-access papers (continued):
Sharing a sentence is not in itself a finding about the gene and the disease.
lymphoma (21 papers, 2013 to 2025). A malignant (clonal) proliferation of B- lymphocytes or T- lymphocytes which involves the lymph nodes, bone marrow and/or extranodal sites. "This analysis suggests that TCF3-bound genes are differentially methylated and are associated with treatment failure in a lymphoma subtype." (PMID 27146673, 2016). "B-lymphoblastic leukemia/lymphoma with TCF3::PBX1 fusion is typically strongly positive for CD9, dim-to-negative for CD34, and dim-to-negative for CD20." (PMID 40227608, 2025). "Subsequently, after knocking down the TCF3, the proliferation rate of lymphoma cells was dramatically lower, while the apoptosis rate was distinctly higher (P < 0.01)." (PMID 34658308, 2021). "After determining the functions of TCF3 and miR-101 in lymphoma cells, we further examined their molecular mechanisms." (PMID 34658308, 2021). "We extended the analysis of the differential expression of the E47 and E12 TCF3 isoforms to adult GCB-lymphomas other than BL." (PMID 30926794, 2019). "The TCF3/PBX1 gene fusion is a recurrent genetic abnormality in pediatric B-lymphoblastic leukemia/lymphoma (B-ALL/LBL)." (PMID 31575852, 2019). "For example, SHMT2 knockdown disrupted the TCF3 transcriptional survival program in lymphoma." (PMID 36213384, 2022). "QRT-PCR was used to detect the expression of TCF3 and miR-101 in BL tissues and lymphoma cells." (PMID 34658308, 2021). "Specifically, SuperDendrix finds associations between increased dependency on the transcription factor TCF3 and the mutually exclusive set {myeloma, BCL2(A)} and the transcription factor IRF4 and {myeloma, lymphoma}." (PMID 35382456, 2022). "We found that the expression of TCF3 and HDAC3 was up-regulated in BL tumor tissues and lymphoma cells, and the miR-101 expression was down-regulated." (PMID 34658308, 2021). "Genes frequently mutated in BL are located in the BL-specific spot A (e.g. ID3, CCND3) and D (e.g. TCF3, SMARCA4, MYC) indicating their increased activity in BL and partly in intermediate lymphomas." (PMID 31039827, 2019). "Immunoblot analysis of tumor extracts confirmed that cellular proteins that are highly expressed in GC B cells, including cyclin D3, GCSAM, TCL1, Myb, TCF3 and BACH2 are expressed at higher levels in the ΔEBNA2 + Myc lymphomas in comparison to the ΔEBNA2 alone lymphomas." (PMID 38620028, 2024). "Skewing towards the E47 expression seems to be particularly pronounced in BL as compared to other mature GCB-lymphomas and, thus, likely contributes to deregulation of the TCF3/ID3 complex particularly in BL lacking ID3 and/or TCF3 mutations." (PMID 30926794, 2019). "Mice lacking E2a/Tcf3 develop lymphomas, suggesting that E2A is a tumor suppressor." (PMID 35401501, 2022). "B-lymphoblastic leukemia/lymphoma with TCF3::PBX1 fusion has also been reported to overexpress CD58 and CD81 when compared with cases of B-lymphoblastic leukemia/lymphoma without cytogenetic alterations or with other cytogenetic abnormalities." (PMID 40227608, 2025).
colorectal cancer (18 papers, 2007 to 2025). A primary or metastatic malignant neoplasm that affects the colon or rectum. "Upregulation of TCF3 expression, associated with promoter hypomethylation is in accordance with previously published literature observed in colorectal cancer." (PMID 29755656, 2018). "Meanwhile, the TCF3 sub-module (Mod107) was enriched in transcriptional regulators of epidermal and embryonic stem cells, consistent with that stem-like properties were associated with decreased benefit from chemotherapy in colorectal cancer." (PMID 29237416, 2017). "Previous studies have reported that the diminished activity of TCF3 plays a role in lymphoid malignancies, and up-regulation of it is involved in the development and progression of colorectal cancer." (PMID 28651018, 2017). "In colorectal cancers it has been shown that β-catenin/TCF4 complexes compete with TCF3 to bind to the MYC promoter, and β-catenin/TCF4 induces its expression while TCF3 represses it." (PMID 27228072, 2016). "Relationships between clinicopathologic features and TCF3 expression in colorectal cancer." (PMID 25375219, 2014). "Our study delves into the intricate regulatory mechanisms of Activating transcription factor 3 (ATF3) on Cystathionine β-synthase (CBS) under cystine deprivation stress, conferring resistance to ferroptosis in colorectal cancer (CRC) cells." (PMID 38490069, 2024). "In studies of mouse and human colorectal cancer, SPDEF induces a quiescent state of cancer cells by disrupting the binding of β-catenin to TCF1 and TCF3 and by regulating genes that control the cell cycle." (PMID 36809297, 2023). "This study aims to investigate the role of TCF3 in predicting prognosis of patients with stage II and III colorectal cancer (CRC)." (PMID 25375219, 2014).
Burkitt lymphoma (17 papers, 2015 to 2025). A rare form of malignant mature B-cell non-Hodgkin lymphoma. "A further demonstration of the importance of the relative expression of the TCF3 isoforms comes from the study of mutations in the TCF3-exon 18b HNRNPH-binding site observed in a subset of Burkitt lymphomas." (PMID 40766465, 2025). "Accordingly, Id3 mutations have been observed in more than 50% of all Burkitt lymphomas, and the presence of Id3 and/or TCF3 mutations has been detected in 70% of sporadic Burkitt lymphomas." (PMID 28122577, 2017). "Genomic studies of Burkitt’s lymphomas found TCF3 to be among the most mutated genes and 70% of patient samples were identified with heterozygous TCF3 deletions in Sezary syndrome cells, an aggressive T cell lymphoma." (PMID 26029241, 2015). "•EBV-negative Burkitt lymphoma is more dependent on ID3/TCF3/CCND3 axis deregulation compared to EBV-positive Burkitt lymphoma." (PMID 41297313, 2025). "A study has pointed out that TCF-3 gene expression has been found to be up-regulated in all three subtypes of Burkitt lymphoma." (PMID 34658308, 2021). "To further determine the function of TCF3 in Burkitt lymphoma, we knocked down TCF3 in Namalwa and Raji cells and tested its influence on cell proliferation, apoptosis, and cell cycle." (PMID 34658308, 2021). "This study aims to reveal the effect of TCF3 on the pathogenesis of Burkitt lymphoma and provide a reliable basis for clinical treatment." (PMID 34658308, 2021). "Another marker, an important transcription factor TCF3 played a role in germinal center B - cell development and promoted cell growth, which contributed to proliferative phenotype in Burkitt lymphoma." (PMID 34527446, 2021). "In Burkitt lymphoma missense mutations of Id3 have been found, which lead to mutated HLH domain and altered ability of Id3 to inhibit TCF3 and/or TCF4." (PMID 28122577, 2017). "However, there are few studies on the mechanism of how the transcription factor TCF-3 mediates the occurrence and development of Burkitt lymphoma." (PMID 34658308, 2021). "In RAJI cells (Burkitt lymphoma) and SLVL cells (splenic B cell lymphoma), mutations of DNA-binding protein inhibitor ID-3 (ID3), transcription factor 3 (TCF3), and neurogenic locus notch homolog protein 2 (NOTCH2) increase phosphorylation of proteins in Akt/mTOR pathway." (PMID 33490663, 2021). "qRT-PCR was performed to determine the expression of TCF3, histone deacetylase 3 (HDAC3), and microRNA-101 (miR-101) in the Burkitt lymphoma (BL) tumor tissues and lymph node tissues with reactive lymph node hyperplasia (RLNH)." (PMID 34658308, 2021). "So far, it can be seen that the highly expressed transcription factor TCF3 in Burkitt lymphoma can recruit HDAC3 in the miR-101 promoter region, inhibit miR-101 expression, and regulate the activity of the Akt/mTOR pathway, thereby improving the biological performance of Burkitt lymphoma cells." (PMID 34658308, 2021).
agammaglobulinemia (10 papers, 2017 to 2024). A decreased level of serum immunoglobulins. "In contrast, the heterozygous TCF3 DN variant was highly deleterious despite unimpaired protein expression, resulting in complete B-cell deficiency and agammaglobulinemia." (PMID 39073655, 2024). "Complete AR TCF3 deficiency is associated with reduced B cells, hypogammaglobulinemia, dysmorphic phenotypes, and B-cell acute lymphoblastic leukemia (B-ALL)." (PMID 39073655, 2024). "In this study, we describe the first Asian patient with agammaglobulinemia caused by the TCF3 p.E555K variant and provide insights into the structure and function of this variant." (PMID 39073655, 2024). "Patients with AR TCF3 deficiency exhibited relatively broad phenotypes, including not only B-cell deficiency and agammaglobulinemia, but also facial dysmorphic features and B-ALL." (PMID 39073655, 2024). "The heterozygous TCF3 DN variant was first shown to be responsible for an AD form of agammaglobulinemia in 2013." (PMID 39073655, 2024). "Biallelic nonsense TCF3 variants were also identified in two individuals with B cell deficiency and hypo/agammaglobulinemia." (PMID 37273190, 2023). "Recently, individuals with B lymphopenia, agammaglobulinemia, and recurrent sinopulmonary infections due to mutations in TCF3, SPI1, PAX5, IKZF1, or IKZF3 have been reported." (PMID 37273190, 2023). "Mutations in TCF3 gene have been related to immunodeficiencies and have been described in agammaglobulinemia with an autosomal dominant pattern of inheritance." (PMID 35281075, 2022). "Monogenic mutations in TCF3 are known to cause antibody deficiency by homozygous and heterozygous mutations." (PMID 36072607, 2022). "One of these patients also harbored a pathogenic mutation in TCF3 (E555K), which causes an autosomal dominant form of agammaglobulinemia." (PMID 29867917, 2018). "In another recent study, four unrelated individuals with de novo heterozygous E55K missense mutations of TCF3 presented with a severe B-cell defect and agammaglobulinemia, and here a dominant negative mechanism was suggested." (PMID 29114388, 2017). "The TCF3 DN variant leading to qualitative impairment of the E47 transcription factor was first described in 2013 in 4 independent patients with recurrent bacterial infections and agammaglobulinemia." (PMID 39073655, 2024). "Agammaglobulinemia with other inherited pattern were also concluded: AR agammaglobulinemia was associated with mutations in several other genes such as IGHM, IGLL1, CD79A, CD79B, BLNK, PIK3R1, and TCF3 genes; AD-related agammaglobulinemia was also found with LRRC8A and TCF3 gene mutations." (PMID 36140582, 2022). "Indeed, we did recently report a patient with a homozygous nonsense mutation in TCF3 gene, who presented with severe hypogammaglobulinemia, very low number of B cells and developed B-cell acute lymphoblastic leukemia." (PMID 28702026, 2017). "TCF3 HI presented with hypogammaglobulinemia, reduced total B cells, switched memory B cells, plasmablasts, and an intermediate reduction of in vitro plasmablast generation and immunoglobulin production." (PMID 39073655, 2024). "In addition, we identified another mode of inheritance for the previously reported AD agammaglobulinemia due to heterozygous dominant-negative de novo mutation in transcription factor 3 (TCF3) gene." (PMID 28702026, 2017). "(i) TCF3 haploinsufficiency (HI) also impacts both TCF3 isoforms, resulting in common variable immunodeficiency (CVID) with low B cells and hypogammaglobulinemia." (PMID 39073655, 2024).
lung cancer (10 papers, 2013 to 2024). A malignant neoplasm involving the lung. "The transcription factor 3 gene (TCF3) is a key TF overexpressed in lung cancer and is mainly involved in the cell cycle, cell division, and proliferation." (PMID 39228892, 2024). "Interestingly, the TCF3 expression level was negatively correlated with the prognosis of patients with gastric cancer (HR = 1.45,P < 0.001) and lung cancer (HR = 1.45,P < 0.001)." (PMID 39205642, 2024). "The global transcriptomic network analysis highlighted the impact of five TFs, SOX4, TCF3, TEAD4, ETV4, and FOXM1, in gut and lung cancer." (PMID 39228892, 2024). "In lung cancer, SOX4 expression is probably related to the overregulation of WNT5A; then, SOX4, FOXM1, TCF3, and JUP might form a stable protein complex with other factors and co-factors for the regulation of transcriptional targets." (PMID 39228892, 2024). "E2F1 is overregulated in seven lung cancer datasets and is related to: 1) HPV infection; 2) HBV and EBV virus infection along with E2F3; 3) the cell cycle and pathways in cancer along with E2F3; and 4) HTVL-I infection along with E2F3 and TCF3." (PMID 39228892, 2024). "CRX, TCF3, and GABP were predicted as novel putative transcription factors in lung cancer." (PMID 28592245, 2017).
colon cancer (9 papers, 2016 to 2024). "Positive autoregulation has been described before for LEF1 in colon cancer, XTcf-4 (Tcf7l2) in Xenopus midbrain and zebrafish Tcf3 (Tcf7l1)." (PMID 29942461, 2018). "TCF3 upregulation is caused by promoter hypomethylation during development, colon cancer progression, and the transcriptional upregulation of multiple cyclin-dependent kinase inhibitors like CDKN1A, p15INK4B, and p16INK4B, and probably CDKN3 in colon cancer." (PMID 39228892, 2024). "Additionally, TCF3 participates in the regulation of colon cancer initiation, EMT, metastasis, and pancreatic cancer cell proliferation." (PMID 39205642, 2024). "Low expression of Socs3 and Tcf3 have been associated with the occurrence and progression of CRC, while upregulation of Fas and Il15 is associated with malignant potential in colon cancer cells by promoting tumor motility and metastasis." (PMID 34843459, 2021). "The regulatory function of TEAD4, TCF3, ETV4, SOX4, and FOXM1, over other key TFs and common DEGs, was highlighted in colon cancer, establishing key co-regulatory complexes." (PMID 39228892, 2024). "HTLV-1 Tax acts on genes indirectly by binding several TFs, such as TCF3, ELK1, and MYC in colon cancer, as well as POLB, BUB3, and CDK4, according to the HTLV-1 infection signaling pathway." (PMID 39228892, 2024). "In colon cancer, TCF3 has been reported to induce MYC transcriptional activation, but we found that OCT4 has a greater role in MYC transcription than TCF3." (PMID 32409685, 2020). "In colon cancer, TEAD4 may also form a complex with TCF3 under the regulation of Wnt." (PMID 39228892, 2024).
gastric cancer (9 papers, 2017 to 2024). A primary or metastatic malignant neoplasm involving the stomach. "TCF3 was linked with drug resistance in gastric cancer, but this gene may be responsible for drug resistance in EOC." (PMID 30970615, 2019). "In colorectal and gastric cancer, TCF3 isrelated to proliferation stimulation and metastasis, and inskin cancer, TCF3 knockdown decreased tumor growth andaggressiveness." (PMID 38100720, 2023). "SNHG16 sponged miR-135a and promoted Janus-activated kinase 2 (JAK2) and transcription Factor 3 (STAT3) expression in gastric cancer." (PMID 36949429, 2023). "Besides, TCF3 can also be transcriptionally active WDR5 and involved in miR-17-5p and HOXA11-AS activation, which results in poorer prognosis in gastric cancer." (PMID 36829181, 2023).
prostate carcinoma (9 papers, 2009 to 2025). A carcinoma that arises from epithelial cells of the prostate gland. "TCF3, a transcription factor, has been reported to be upregulated in prostate cancer and positively associated with cancer cell development." (PMID 40610429, 2025). "Previous researches have indicated an association between the overexpression of TCF3 and different cancers, including breast, colorectal, cervical, prostate cancers, and GC." (PMID 34700372, 2022). "The expression of TCF3 (E2A) is enhanced in prostate cancer, thereby promoting tumor progression—it provides resistance to apoptosis in prostate cancer." (PMID 31614829, 2019). "TCF3 is involved in the Wnt/β-catenin signaling pathway, which crosstalks with AR signaling in prostate cancer." (PMID 23034120, 2012).
B-cell acute lymphoblastic leukemia (6 papers, 2018 to 2026). A neoplasm of lymphoblasts committed to the B-cell lineage, typically composed of small to medium-sized blast cells. "Microarray technology has evidenced the gain of genes, previously known to be constitutively expressed in cHL, like STAT6 (12q31), NOTCH1 (9q34), JUNB (19p13) and, recently, TCF3 or E2a (19p13.3), associated also with pre-B cell acute lymphoblastic leukemia." (PMID 30634664, 2019).
cervical cancer (6 papers, 2019 to 2025). A primary or metastatic malignant neoplasm involving the cervix. "It was found that TCF3, displaying the highest NES value, was up-regulated in cervical cancer and its down-regulation significantly inhibited the growth and invasion of cervical carcinoma cells." (PMID 31523389, 2019). "Activated transcription factor 3 (ATF3) was a stress-induced transcription repressor, it had been shown that ATF3 overexpression enhanced paclitaxel apoptosis in cervical cancer HeLa cells in part by stimulating TAp73, thus, it can act as a tumor suppress factor." (PMID 37914994, 2023).
glioma (6 papers, 2013 to 2024). A benign or malignant brain and spinal cord tumor that arises from glial cells (astrocytes, oligodendrocytes, ependymal cells). "Our data show that TCF3 is represented in the list of the top 10 activated TFs of all analyzed glioma NS, except BR2." (PMID 36231068, 2022). "TCF3 also promotes glioma development through PI3K/Akt and MAPK-Erk signaling pathways." (PMID 36231068, 2022). "However, a growing body of new data on TCF3 points to the high importance of genes controlled by TCF3 and TCF3 itself in the development and invasion of glioma cells." (PMID 36231068, 2022). "Thus, the STAT3-dependent (as well as SOX2- and TCF3-dependent) increase in ERRFI1 expression provides the common glioma path for the regulation of EGFR signaling." (PMID 36231068, 2022). "It was observed that NS formation is accompanied by the activation of five common gliomas of TFs, SOX2, UBTF, NFE2L2, TCF3 and STAT3." (PMID 36231068, 2022). "TCF3 (Transcription factor 3) is a member of the T-cell factor/lymphoid enhancer factor (TCF/LEF) family, and high levels of TCF3 in glioma potentially promote glioma development through the Akt and Erk pathways." (PMID 33537074, 2021). "Accordingly, the enrichment of the glioma’s overlapping activated genes in those controlled by TCF3 is not highly statistically significant (Enrichr p-value < 0.01; adjusted p-value > 0.05)." (PMID 36231068, 2022). "Finally, we found that TCF3 showed highly positive correlation with PTBP1 in glioma and was significantly higher in glioma compares to normal tissues (P < 0.001, r = 0.7)." (PMID 35299889, 2022).